MOG (myelin oligodendrocyte glycoprotein)
Diseases named in the same sentence as MOG in open-access papers (continued):
Sharing a sentence is not in itself a finding about the gene and the disease.
encephalitis (continued). "In addition, for children suspected of encephalitis showing no response to anti-infective therapy, as well as those experiencing epilepsy recurrence without identifiable triggers, especially when cranial MRI reveals cortical lesions, vigilance for MOG-Ab associated encephalitis is warranted." (PMID 40740785, 2025). "It is worth noting that CCE is often misdiagnosed as autoimmune encephalitis or viral encephalitis initially because MOG antibody screening is not considered." (PMID 40098969, 2025). "We report a case of an 80-year-old man with imaging-negative MOG antibody encephalitis without focal neurological deficits." (PMID 39493140, 2024). "This study aimed to report about a patient with encephalitis showing both anti-NMDAR and anti-MOG antibodies who responded favorably to steroids and to review and discuss existing literature on the effectiveness of steroid therapy during the early stages of this condition." (PMID 38895128, 2024). "Therefore, based on their history and symptoms, we recommend measuring anti-MOG antibodies in patients who respond well to steroids, even if anti-NMDAR encephalitis is suspected." (PMID 38895128, 2024). "And these mice preferentially showed ON when immunized with MOG35-55 peptide and MOG protein without showing encephalitis or myelitis." (PMID 37686172, 2023). "MOG-IgG and NMDAR-IgG coexistence is the most common antibody coexistence syndrome, which may manifest as encephalitis and demyelination." (PMID 36009058, 2022). "In the study, we did not detect MOG-IgG in any other patient neither in the VZV group (including 15 with VZV encephalitis/myelitis) nor in the neuroborreliosis group." (PMID 34737756, 2021). "In the past few years, patients with MOG-ab and encephalitis or encephalitic symptoms who did not fulfill the criteria of ADEM were reported in several research." (PMID 34691028, 2021). "Before 2017, the differential diagnosis pointed to the possibility that some patients had a MOG antibody encephalitis, but we were not able to carry out the adequate testing." (PMID 33264341, 2020). "Bearing in mind that the patients previously were not tested for MOG antibody encephalitis, it is possible that some patients were positive, but the clinical course of the disease in our patients was most consistent with PedMS." (PMID 33264341, 2020). "Based on the combination of clinical features and laboratory evidence, the patient was diagnosed with an anti-MOG inflammatory demyelinating disease, though the anti-NMDAR antibody titer was too low to establish a definitive diagnosis of anti-NMDAR encephalitis." (PMID 31866928, 2019). "We also compared anti-NMDAR encephalitis with and without co-positive MOG antibody, as well as specific autoantibody-positive AE and autoantibody-negative but probable AE." (PMID 31507515, 2019). "Perivascular cuffing, a classic feature of encephalitis, was not seen in the brains of MOG-primed mmp7-/- mice." (PMID 19267908, 2009). "Clinicians ought to maintain a high degree of clinical suspicion for MOG antibody encephalitis even in the absence of typical radiographic abnormalities, as prompt recognition and treatment initiation are essential to mitigate adverse sequalae associated with this condition." (PMID 39493140, 2024). "Even with a low incidence of tumors, the MOG-AD, anti-NMDAR encephalitis, and MNOS patients were prone to fever, vomiting, and headache/dizziness, suggesting that infectious factors may be the main cause of antibody-mediated CNS autoimmune diseases in children." (PMID 38249740, 2023). "Additionally, two adult patients were retrospectively diagnosed with anti-MOG encephalitis, with prior negative ANeA testing." (PMID 37954587, 2023). "However, in previous literature, cases who had MOG-IgG and encephalitis without demyelination had already been reported, and MOG-IgG was thought of as responsible for the isolated encephalitis." (PMID 34691028, 2021).
encephalitis (continued). "Myelin oligodendrocyte glycoprotein (MOG) antibodies are most often found in relapsing optic neuritis or neuromyelitis optica spectrums diseases, acute demyelinating encephalomyelitis (ADEM) and in a few cases with encephalitis, complicated by respiratory impairment." (PMID 34635185, 2021). "While multiple reports of image-positive MOG antibody encephalitis have allowed clinicians to understand the disease and its implications, the presentation and prognosis of image-negative MOG antibody encephalitis are not as well elucidated in the current literature." (PMID 39493140, 2024). "The reason for the response of patients with anti-NMDAR and anti-MOG antibody overlapping encephalitis to steroid therapy is not yet completely understood; however, it may be explained by the involvement of anti-MOG antibodies in the pathogenesis of the disease." (PMID 38895128, 2024). "Furthermore, co-existing myelin oligodendrocyte glycoprotein antibody (MOG-Ab) in patients diagnosed with anti-NMDAR encephalitis is not rare, and this subpopulation of patients may have different response to treatment according to previous studies." (PMID 34268281, 2021). "The patients with MOG antibody positive associated demyelination showed predominant elevation of B cell related cytokine/chemokines (CXCL13, APRIL, BAFF and CCL19) compared to MOG antibody negative demyelination group as well as other encephalitis groups (CXCL13 and CCL19)." (PMID 27575749, 2016). "Previous retrospective studies showed that the clinical phenotype of patients with double positivity for MOG-IgG and NMDAR-IgG was more prone to encephalitis when compared to MOGAD patients without NMDAR-IgG." (PMID 36009058, 2022). "Unlike the previous study of patients with encephalitis other than ADEM who had worse outcomes, patients with these phenotypes in our cohort all became MOG-ab seronegative and reached full recovery at last follow-up despite the relapsing course." (PMID 33841310, 2021). "With positive MOG-IgG and NMDAR-IgG, the two cases fulfilled the criteria for anti-NMDAR encephalitis, but not MOGAD for the absence of demyelination." (PMID 34691028, 2021). "None of the eight patients tested for SARS-CoV-2 PCR in CSF were positive, and none of the autoantibodies seen in autoimmune forms of encephalitis (NMDAR, LGI1) or encephalomyelitis (AQP4, MOG) were detected in serum or CSF samples." (PMID 32637987, 2020). "Comparison between combined MOG antibody-positive and -negative children with anti-NMDAR encephalitis." (PMID 31507515, 2019). "This retrospective study enrolled 10 MNOS pediatric patients, 50 MOG-AD (anti-NMDAR antibody-negative), and 81 anti-NMDAR encephalitis (MOG antibody-negative) pediatric patients who were admitted from July 2016 to June 2022 and used their clinical data for comparison." (PMID 38249740, 2023). "In the MOG-Ab-positive group, non-ADEM encephalitis (26.7%) was second in incidence only to ADEM." (PMID 36401212, 2022).
myelitis (134 papers, 2011 to 2026). An inflammatory process affecting the spinal cord. "We clinicoradiologically and serologically characterized patients with myelitis associated with rheumatologic disease evaluated in the era of availability of MOG-IgG and more sensitive AQP4-IgG cell-based assays." (PMID 39442039, 2025). "We report a case of a 29-year-old male patient with extremely longitudinally extensive myelitis ultimately diagnosed as myelin oligodendrocyte glycoprotein-associated disease (MOGAD)." (PMID 38854217, 2024). "Although 41.8% of patients with MOG-IgG-associated myelitis have a prodromal event, such as infection or vaccination, before disease onset, our study revealed such cases in 41.7% of patients; however, no vaccination was found." (PMID 38020648, 2023). "This study provides clinical, CSF, and MRI evidence for recognizing and differentiating GFAP-IgG-and MOG-IgG-associated myelitis." (PMID 38020648, 2023). "Our study showed that patients with MOG-IgG-associated myelitis frequently had involvement of the cervical and thoracic spinal cords, while conus involvement was rare." (PMID 38020648, 2023). "Eleven of our patients with MOG-IgG-associated myelitis underwent cranial enhancement scans, and six (54.5%) showed patchy enhancement." (PMID 38020648, 2023). "In contrast, compared to previous studies [16/54 (30%)], MOG-IgG-associated myelitis was more prevalent in children (66.7%)." (PMID 38020648, 2023). "This study retrospectively compared the clinical features, CSF and imaging features, and overlapping antibodies in 14 and 24 patients with GFAP-IgG-and MOG-IgG-associated myelitis, respectively." (PMID 38020648, 2023). "A study reported elevated CSF protein levels in 77% of the 35 patients with MOG-IgG-associated myelitis." (PMID 38020648, 2023). "Demographic and clinical characteristics of patients with GFAP-IgG and MOG-IgG-associated myelitis [n (%)]." (PMID 38020648, 2023). "In a study of 54 patients with MOG-IgG-associated myelitis, 24 (44%) were females, while 15 (39.5%) were females in another study." (PMID 38020648, 2023). "In contrast, among the 24 patients with MOG-IgG-associated myelitis, the condition was equally divided between males and females, with a median age of onset of 9.5 years and more in children (66.7%) than in adults." (PMID 38020648, 2023). "Overall, 14 and 24 patients with GFAP-IgG-and MOG-IgG-associated myelitis, respectively, were retrospectively screened and included in the study." (PMID 38020648, 2023). "In cranial MRI, patchy gadolinium enhancement was less common in patients with GFAP-IgG-associated myelitis than in those with MOG-IgG-associated myelitis, with a significant difference (p < 0.05)." (PMID 38020648, 2023). "Glial fibrillary acidic protein-immunoglobulin G (GFAP-IgG)-associated myelitis and myelin oligodendrocyte glycoprotein-IgG (MOG-IgG)-associated myelitis have rarely been compared." (PMID 38020648, 2023). "MOG-IgG can lead to ON, myelitis, and ADEM and are currently associated with anti-n-methyl-d-aspartate (NMADA) antibody encephalitis, teratoma, COVID-19, etc.." (PMID 35370624, 2022). "In our review of the literature, we have found only one other reported case of COVID-19-related new-onset MOG-associated myelitis, presented in the setting of concurrent infection." (PMID 35399911, 2022). "We identified 2 case reports and 1/10 patients in a case series with MOG antibody-associated myelitis in association with a VZV infection; in addition, there are 9 reports of AQP4 antibody-associated CNS disorders in patients with VZV infections." (PMID 34737756, 2021). "Similar to our case, MOG-IgG associated myelitis is characterized in the MRI by longitudinally extensive T2 hyperintense lesions affecting mainly the grey matter and lack of contrast enhancement." (PMID 34737756, 2021).
myelitis (continued). "Younger children tend to have longitudinally extensive myelitis, such as with MOG-antibody associated myelitis and idiopathic TM, so this characteristic of anti-AQP4 antibody-mediated NMOSD is less specific in the pediatric population." (PMID 31109018, 2019). "In contrast, acute flaccid myelitis has predominantly gray matter involvement, and mixed patterns have been observed in MOG-antibody associated myelitis." (PMID 31109018, 2019). "This would again result in a substantial loss of patients at high risk of MOG-EM, since those criteria require a history of both ON and myelitis and would thus be inappropriate." (PMID 29724224, 2018). "While ADEM is the predominant clinical association in young children, in older children with MOG antibodies there is a shift towards presentation with ON, myelitis, and/or brainstem symptoms." (PMID 29724224, 2018). "63.6 % (14/22) of all MOG-IgG-positive patients with a history of both ON and myelitis met Wingerchuk’s 2006 revised diagnostic criteria for NMO." (PMID 27793206, 2016). "In summary, our study demonstrates that MOG-IgG-associated ON and myelitis frequently follow a relapsing course and result in severe and/or persisting disability in a substantial number of cases." (PMID 27793206, 2016). "While the association of MOG-IgG with ON and myelitis is now well established, less is known about extra-opticospinal manifestations in MOG-IgG-related autoimmunity." (PMID 27802825, 2016). "Additionally, MOG antibodies (MOG-IgG) were present in the serum and CSF, leading to the diagnosis of MOG-IgG-associated myelitis induced by immunization following influenza vaccination." (PMID 42200184, 2026). "The reason why MOG-IgG may be associated with a lower risk of spinal movement disorders in myelitis patients is unclear and likely reflects the pathophysiological differences between the two conditions." (PMID 38977461, 2024). "An additional diagnostic clue could be the identification of antibodies associated with myelitis, such as MOG‐IgG and AQP4–IgG." (PMID 39222058, 2024). "Finally, 24 patients with MOG-IgG-associated myelitis were included, of whom 11 and 13 were positive for MOG-IgG in the serum and in both CSF and serum, respectively." (PMID 38020648, 2023). "CSF findings of GFAP-IgG and MOG-IgG-associated myelitis [n (%)]." (PMID 38020648, 2023). "Additionally, 21 of 24 patients (87.5%) with MOG-IgG-associated myelitis had intracranial lesions, which were characterized by abnormal signals on T2WI/FLAIR (Figures 3B1,B2)." (PMID 38020648, 2023). "LETM and short-segment lesions were found in 12 (57.1%) and 9 (42.9%) patients with MOG-IgG-associated myelitis, similar to previous reports, which showed that LETM is the predominant pattern in MOG-IgG-associated myelitis; however, short-segment lesions are also common." (PMID 38020648, 2023). "MRI lesions of the spinal cord in patients with MOG-IgG-associated myelitis, predominantly involving the central gray matter, were limited to the axial sequence of only one patient (4.2%) exhibiting a more pronounced “H sign,” which differs from the findings of previous studies." (PMID 38020648, 2023). "Furthermore, 3 (12.5%) of 24 patients with MOG-IgG-associated myelitis had isolated myelitis, all of whom were adults." (PMID 38020648, 2023). "MRI characteristics of GFAP-IgG and MOG-IgG-associated myelitis [n (%)]." (PMID 38020648, 2023). "Therefore, this study retrospectively analyzed and compared the clinical features of GFAP-IgG-and MOG-IgG-associated myelitis to better understand the clinical diagnosis and management processes." (PMID 38020648, 2023). "The median age of onset of GFAP-IgG-associated myelitis was later than that of the MOG-IgG group." (PMID 38020648, 2023). "In particular, the clinical presentation of myelitis in the context of MOG-associated disease may be similar with AFP of the limbs and predominant grey matter abnormalities of the spinal cord on MRI." (PMID 36268734, 2022).
myelitis (continued). "This may, at least in part, reflect the substantially higher proportion of patients with myelitis (which is generally associated with higher CSF WCCs in MOG-EM than other manifestations) in the present series." (PMID 35737110, 2022). "Anti-myelin oligodendrocyte glycoprotein (MOG) antibody-associated myelitis is ademyelinating inflammatory disorder associated with the presence of theimmunoglobulin G antibody against MOG, being most common in the third decade oflife, with a predilection for females." (PMID 34866702, 2021). "Moreover, there has been a previous report in which MOG-IgG-positive myelitis has been associated with thyroid gland disease while these findings should currently not be overemphasized due to the high prevalence of thyroid diseases." (PMID 32055995, 2020). "The 15 cases presented here were identified as part of a large European cohort (n = 50) of MOG-IgG-positive patients reported in part 1 and part 2 of this series, suggesting a relatively high frequency (30 %) of brainstem involvement among patients with MOG-IgG-associated myelitis and/or ON." (PMID 27802825, 2016). "Simultaneous ON and myelitis as well as bilateral ON at onset may thus be of diagnostic value and should prompt physicians to consider MOG-IgG testing." (PMID 27793206, 2016). "Therefore, we hypothesized that GFAP-IgG-associated myelitis is more likely to be associated with elevated CSF protein levels and is more significantly increased than MOG-IgG-associated myelitis, which may indicate a severe inflammatory response in the CNS." (PMID 38020648, 2023). "The limitations include a potential referral bias due to the possibility that patients with ON and/or myelitis may have been preferentially referred for MOG-IgG testing as a consequence of the close association of MOG-IgG with these two conditions reported in the previous literature." (PMID 27788675, 2016). "The positivity rate of MOG-Abs was highest among patients with cortical encephalitis, followed by those with myelitis and ADEM." (PMID 41515652, 2026). "Patient 13 experienced a recurrence of myelitis and ON 5 months later, with MOG-IgG reverting to positive." (PMID 40777035, 2025). "Of note, 1 patient with psoriatic arthritis who developed myelitis due to MOGAD (MOG-IgG 1:1,000 by live CBA) was receiving the anti–tumor necrosis factor (TNF)-α agent adalimumab." (PMID 39442039, 2025). "50.0% (26/52) lesion enhancement were found in children with MOG-antibody-positive myelitis, which is the most common." (PMID 39318613, 2024). "MOGAD myelitis is diagnosed when a patient has neurological deficits and tempo of symptomatic development compatible with myelitis, a clear positive serum MOG-IgG test, and supportive of diagnosis MRI features." (PMID 37483456, 2023). "A finding of exclusively new short lesions during an acute attack of myelitis is more common in MOG-EM/MOGAD (being found at least once in up to 50% of cases over the course of disease in a European cohort) than in NMOSD (10–15%)." (PMID 37022481, 2023). "One report has described HHV-6 reactivation in the central nervous system of a COVID-19 patient with HHV-6 myelitis and concomitant myelin oligodendrocyte glycoprotein antibody-mediated parainfectious myelitis." (PMID 36803914, 2023). "One patient had COVID-19 infection followed by longitudinal myelitis, with positive anti-myelin oligodendrocyte glycoprotein (MOG)." (PMID 36654564, 2022). "The “unclassified” group was named as such at the time of plasma sampling; some of those individuals received diagnoses of CIS, isolated myelitis, and MOG Ab-related disease upon follow-up." (PMID 36326407, 2022). "In a study of MOG antibody-positive individuals, 27/28 patients with a history of clinical myelitis showed spinal cord inflammation on MRI." (PMID 35399911, 2022). "Anti-aquaporine-4 and anti-myelin oligodendrocyte glycoprotein IgG antibodies should be measured especially in the context of myelitis." (PMID 36388212, 2022).